ATP6AP1 (ATPase H+ transporting accessory protein 1)
Diseases named in the same sentence as ATP6AP1 in open-access papers (continued):
Sharing a sentence is not in itself a finding about the gene and the disease.
breast carcinoma (continued). "Furthermore, we blocked autophagy by knocking down ATG5, and demonstrated that ATP6AP1 stimulates luminal breast cancer cell proliferation and TAM resistance through autophagy activation." (PMID 40133274, 2025). "ATP6AP1 could serve as both a specific biomarker and a potential therapeutic target for luminal breast cancer." (PMID 40133274, 2025). "However, substantial progress is required not only in the laboratory but also in the clinic to certify the role of ATP6AP1 as a therapeutic option for breast cancer patients." (PMID 40133274, 2025). "Therefore, to improve the survival rate of breast cancer patients and overcome chemotherapy resistance, our focus is on the interplay between ATP6AP1 and autophagy." (PMID 39627767, 2024). "Additionally, salivary autoantibodies against ATP6AP1 have been explored as potential tools for efficiently screening early cases of breast cancer." (PMID 39627767, 2024). "Future research could employ more sophisticated techniques, such as gene editing and protein–protein interaction analyses, to reveal in greater detail and comprehensiveness the exact mechanisms of ATP6AP1 in the development of drug resistance in breast cancer." (PMID 39627767, 2024). "In summary, we concluded that ATP6AP1 was frequently increased in breast cancer." (PMID 39627767, 2024). "Interestingly, we also found that upregulation of ATP6AP1 was found among molecular subtypes of breast cancer specifically in luminal subtypes, which were known with poor chemotherapy response in breast cancer." (PMID 39627767, 2024). "ATP6AP1 may facilitate breast cancer progression by inhibiting antitumor immunity and promoting iron metabolism and may be a biomarker for breast cancer prognosis." (PMID 36147483, 2022). "Based on these findings, ATP6AP1 may be used as a biomarker for the prognosis and diagnosis of breast cancer." (PMID 36147483, 2022). "When combined with iron chelators, these drugs targeting ATP6AP1 may exhibit synergistic cytotoxicity against breast cancer cells." (PMID 36147483, 2022). "ATP6AP1 expression was significantly upregulated in breast cancer tissues." (PMID 36147483, 2022). "In our study, we demonstrated that ATP6AP1 may play an important role in immunological suppression and may lead to worse outcomes in patients with breast cancer through TME regulation." (PMID 36147483, 2022). "To clarify its function in breast cancer, we identified the genes and pathways related to ATP6AP1." (PMID 36147483, 2022). "In breast cancer, these genes are likely to participate in the regulatory network of ATP6AP1." (PMID 36147483, 2022). "Therefore, we aimed to establish a link between ATP6AP1 and breast cancer and investigate its prognostic value." (PMID 36147483, 2022). "To date, there are few studies on the relationship between ATP6AP1 and breast cancer." (PMID 36147483, 2022). "According to a recent study, salivary autoantibodies against ATP6AP1 may serve as biomarkers for the early detection of breast cancer." (PMID 36147483, 2022). "In summary, our study demonstrated that ATP6AP1 accelerates the process of autophagy by facilitating V-ATPase-mediated lysosomal acidification and Rab7-dependent lysosome fusion, therefore promoting cell proliferation and drug resistance in luminal breast cancer cells." (PMID 40133274, 2025). "Among them, Atg5 is an important gene in mammalian autophagy, serving as a key promoter of early autophagy.To determine whether ATP6AP1 promotes luminal breast cancer cell proliferation and TAM resistance through autophagy activation, we blocked autophagy by knocking down ATG5 using specific shRNA." (PMID 40133274, 2025). "Therefore, ATP6AP1 could serve as both a specific biomarker and a potential therapeutic target for luminal breast cancer." (PMID 40133274, 2025). "The higher expression of ATP6AP1 might be a druggable target for DOX resistance in breast cancer." (PMID 39627767, 2024).
breast carcinoma (continued). "However, it is currently unclear whether ATP6AP1 regulates autophagy in breast cancer cells undergoing chemotherapy and the specific impact of ATP6AP1 on chemotherapy resistance in breast cancer." (PMID 39627767, 2024). "Thus, ATP6AP1 overexpression in breast cancer tissues may inhibit cytotoxic activity against tumor cells, leading to a poor prognosis based on immune infiltration analysis." (PMID 36147483, 2022). "Moreover, the Kaplan-Meier method shows that ATP6AP1 expression levels in patients with breast cancer might predict overall survival, with higher levels suggesting a worse result." (PMID 36147483, 2022). "Our study provides proof that ATP6AP1 enhances TAM resistance by activating autophagy, which carries significant implications for the clinical management of luminal breast cancer." (PMID 40133274, 2025). "Here, we reported that aberrant overexpression of ATP6AP1 promoted cell proliferation and TAM resistance in luminal breast cancer." (PMID 40133274, 2025). "However, the clinical relevance of ATP6AP1 in breast cancer remains unclear." (PMID 36147483, 2022). "To investigate the connection between ATP6AP1 expression and clinicopathological parameters of patients in the TCGA-BRCA cohort, based on the median value, we separated breast cancer samples into two groups: high expression and low expression." (PMID 36147483, 2022). "Therefore, ATP6AP1 may be used as a biomarker for the diagnosis and prognosis of breast cancer." (PMID 36147483, 2022). "To assess whether ATP6AP1 affects TAM resistance, we first analyzed the prognostic significance of the altered expression of ATP6AP1 in luminal breast cancer patients who received TAM chemotherapy using the Kaplan‒Meier plotter database." (PMID 40133274, 2025). "To further explore the impact of ATP6AP1 on TAM resistance, we verified the effect of CQ (an autophagy inhibitor) or Bafilomycin-A1 (BafA1, a V-ATPase inhibitor) on TAM resistance in luminal breast cancer cells." (PMID 40133274, 2025). "Importantly, knockdown of ATP6AP1 blocks DOX-induced autophagic flux and partially reverses DOX resistance in breast cancer cells." (PMID 39627767, 2024). "We found that the protein levels of CACNA1H, CHPF, SDC1 and ATP6AP1 were higher in breast cancer tissues compared with normal tissues, while the expression levels of IRS2 and NT5E were comparatively lower in breast cancer tissues, and the expression of them is consistent with mRNA level." (PMID 36277284, 2022). "Furthermore, we suggest that patients with breast cancer who have high ATP6AP1 expression may not respond well to immunotherapy." (PMID 36147483, 2022).
Immunodeficiency (8 papers, 2016 to 2023). Failure of the immune system to protect the body adequately from infection, due to the absence or insufficiency of some component process or substance. "Jansen EJ depicted that ATP6AP1 deficiency was capable of leading to immunodeficiency with hepatopathy." (PMID 38327651, 2023). "In 2016, 11 male patients were reported with immunodeficiency and hepatic, gastric and (in some) neurological disease due to X‐linked ATP6AP1 deficiency (ATP6AP1‐CDG)." (PMID 32395412, 2020). "The deficiency of ATP6AP1, an accessory subunit of the vacuolar H+‐ATPase, is a recently characterised N‐ and O‐glycosylation defect manifesting with immunodeficiency, hepatopathy and cognitive impairment." (PMID 32216104, 2020). "Consistent with these animal studies, patients with ATP6AP1/Ac45 deficiency display neurocognitive abnormalities as well as immunodeficiency phenotype associated with hypogammaglobulinemia and hepatopathy." (PMID 32393395, 2020). "In this study, we describe a novel ATP6AP1-linked immunodeficiency and identified disease mutations in ATP6AP1 in 11 male patients with abnormal protein glycosylation." (PMID 27231034, 2016). "Mutation in X-linked ATP6AP1 has been shown to lead to immunodeficiency with cognitive impairment." (PMID 32787845, 2020). "ATP6AP1 gene mutations are involved in congenital disorders of glycosylation (CDG) and affect multiple organ systems, including immunodeficiency and cognitive impairment." (PMID 36552760, 2022). "Human mutations in ATP6AP1 have a distinct phenotype to that of TMEM199 and CCDC115 mutations, resulting in immunodeficiency as well as abnormal glycosylation." (PMID 28296633, 2017). "Screening for abnormal protein glycosylation in plasma of patients with hepatopathy and immune dysfunction with or without neurological symptoms provides a rapid way to identify additional individuals with ATP6AP1 deficiency." (PMID 27231034, 2016).
granular cell tumor (5 papers, 2018 to 2025). An unusual benign or malignant neoplasm characterized by the presence of neoplastic large polygonal cells with granular, eosinophilic cytoplasm which contains abundant lysosomes. "Recent studies have demonstrated that inactivating mutations of ATP6AP1 drive the tumorigenesis of granular cell tumors (GCTs)." (PMID 40133274, 2025). "Previous studies have demonstrated that the loss of ATP6AP1 can be carcinogenic; for instance, an inactivating mutation in ATP6AP1 was proposed to be the driving factor for granular cell tumor development." (PMID 34228637, 2021). "Silencing of ATP6AP1 and ATP6AP2 in vitro resulted in vesicle acidification impairment, endosomal compartmental redistribution and intracytoplasmic granule accumulation that closely mimicked the granular cell tumor phenotype." (PMID 32365590, 2020).
hepatopathy (5 papers, 2016 to 2023). "The dominating clinical symptoms displayed by the present cohort of patients with various ATP6AP1 mutations include hepatopathy and immune abnormalities." (PMID 27231034, 2016).
COVID-19 (4 papers, 2020 to 2022). A disease caused by infection with severe acute respiratory syndrome coronavirus 2. "L37F NSP6 variant, which was associated with asymptomatic COVID-19, exhibited reduced binding to ATP6AP1 and weakened ability to impair lysosome acidification to induce pyroptosis." (PMID 34997207, 2022). "Tumor tissues may be especially prone to SARS-CoV-2 infections, which may downregulate ATP6AP1, ultimately impacting the prognoses of BC patients with COVID-19." (PMID 34228637, 2021).
liver disease (3 papers, 2016 to 2021). "In our cohort, the predominant liver phenotype was observed in MPI-CDG patients, while other CDG like PMM2-CDG, ATP6AP1-CDG were associated with liver disease." (PMID 33407696, 2021). "The authors classified CDG based on liver involvement into two main groups: one with predominant/isolated liver involvement (MPI-CDG, CCDC115-CDG, TMEM199-CDG, ATP6AP1-CDG) and the other associated with liver disease (PMM2-CDG, ALG1-CDG, ALG3-CDG, ALG8-CDG, ALG9-CDG, PGM1-CDG)." (PMID 34291020, 2021).
colorectal cancer (2 papers, 2024). A primary or metastatic malignant neoplasm that affects the colon or rectum. "The role of ATP6AP1 in colorectal cancer (CRC) remains elusive despite its observed upregulation in pan-cancer." (PMID 38369634, 2024). "Recent studies have suggested that ATP6AP1 could serve as a therapeutic target for osteolytic diseases and colorectal cancer." (PMID 39627767, 2024). "Therefore, ATP6AP1 may play a pivotal role in modulating tumor immunity and proliferation, underscoring its potential as a valuable biomarker and therapeutic target in colorectal cancer (CRC)." (PMID 38369634, 2024). "In our study, we investigated the role of ATP6AP1 in colorectal cancer and revealed its prognostic value, functional enrichment pathways, methylation, tumor immune infiltration, and variance analysis between high and low ATP6AP1 expression groups by bioinformatic analysis." (PMID 38369634, 2024).
head and neck carcinoma (2 papers, 2016 to 2022). A carcinoma that arises from the head and neck region. "The ATP6AP1 protein is expressed in numerous tumors, including head and neck carcinoma, lung cancer, and leukemia." (PMID 36147483, 2022). "ATP6AP1 is an ATPase that is expressed in normal tissues such as the brain marrow, blood, nerves and skin, and it is also correlated with several tumours such as head and neck carcinomas, lung tumours, adrenal tumours and various other cancers." (PMID 27585820, 2016).
immunodeficiency 47 (2 papers, 2023 to 2024). Any primary immunodeficiency disease in which the cause of the disease is a mutation in the ATP6AP1 gene. "Whole-exome sequencing identified the ATP6AP1 gene missense variant NM_001183.6:c.938A>G (p.Tyr313Cys) in the hemizygous state, which was previously reported in a patient with immunodeficiency type 47." (PMID 37108612, 2023).
liver failure (2 papers, 2016 to 2020). A liver disease characterized by the liver losing or has lost all of its function. "Our study delineates a case of two severely affected siblings with a new hemizygous variant c.221T>C (p.L74P) in ATP6AP1 gene, who both died due to liver failure before reaching 1 year of age." (PMID 32216104, 2020). "Of note, the presence of the p.E346K mutation predicted a more severe phenotype within the ATP6AP1 disease spectrum, which is in accordance with the early death of two patients (3.2 and 5.1) due to liver failure." (PMID 27231034, 2016).
sarcoidosis (2 papers, 2017 to 2020). Sarcoidosis is a multisystemic disorder of unknown cause characterized by the formation of immune granulomas in involved organs. "The relative gene expression levels for ATP6AP1, CYBB, LAMP2, and SERPINA1 were significantly higher in sarcoidosis monocytes as compared to healthy monocytes." (PMID 28577019, 2017).
adrenocortical carcinomas (1 paper, 2018). "We next sequenced the entire coding region of ATP6AP1 and ATP6AP2 in 103 histologic mimics of GCTs, including paragangliomas (n = 29), schwannomas (n = 25), adrenocortical carcinomas (n = 16), oncocytomas (n = 13), hibernomas (n = 10), and chromophobe renal carcinomas (n = 10)." (PMID 30166553, 2018).
alopecia (1 paper, 2021). Hair loss usually from the scalp. "In ATP6AP1-CDG some symptoms aggravated with age (from sensorineural hearing loss to total deafness, from hair loss to total alopecia)." (PMID 33407696, 2021).
breast adenocarcinoma (1 paper, 2024). "In both ER+ and triple-negative human breast adenocarcinoma cell lines (MCF7 and MDA-MB-231), stable ATP6AP1 depletion led to decreased anchorage-independent growth, and reduced migration in both wound healing and transwell migration/invasion assays." (PMID 38448650, 2024).
breast invasive carcinoma (1 paper, 2024). "ATP6AP1 appears to be upregulated in multiple cancer types, especially breast invasive carcinoma, kidney chromophobe, and skin cutaneous melanoma." (PMID 38448650, 2024).
cholestasis (1 paper, 2017). Impairment of the bile flow caused by obstruction within the liver, or outside the liver in the bile duct system. "In CDG presenting with cholestasis (such as ALG8-CDG, COG6-CDG, COG7-CDG, CCDC115-CDG and ATP6AP1-CDG), nutritional interventions such as in other causes of cholestasis can be necessary." (PMID 29112118, 2017).
coloboma (1 paper, 2021). An abnormality in which a part of a structure in one or both eyes is missing. "These include: connective tissue involvement in ATP6AP1-CDG, midline malformations in PGM1-CDG, chronic diarrhoea in MPI-CDG, inverted nipples and abnormal fat distribution in PMM2-CDG, cataract/coloboma in SRD5A3-CDG, cerebellar hypoplasia in PMM2-CDG and SRD5A3-CDG." (PMID 33407696, 2021).
congenital disorder of glycosylation type IIs (1 paper, 2023). "The congenital disorder of glycosylation type IIs (ATP6AP1-CDG; OMIM# 300972) is a rare X-linked recessive complex syndrome characterized by liver dysfunction, recurrent bacterial infections, hypogammaglobulinemia, and defective glycosylation of serum proteins." (PMID 37108612, 2023).
cystic teratoma (1 paper, 2024). "In summary, amplifications of EVX2, HOXD13, HOXD12, HOXD11, HOXD10, and HOXD9 on 2q31.1, NDUFV1 on 11q13.2, and RPL10, SNORA70, DNASE1L1, TAZ, ATP6AP1, and GDI1 on Xq28 were found in all nine mature cystic teratomas in this study." (PMID 38907278, 2024). "Amplifications and deletions of large DNA fragments were observed in some samples, while amplifications of EVX2 and HOXD9-HOXD13 on 2q31.1, NDUFV1 on 11q13.2, and RPL10, SNORA70, DNASE1L1, TAZ, ATP6AP1, and GDI1 on Xq28 were found in all nine mature cystic teratomas." (PMID 38907278, 2024).
glioma (1 paper, 2022). A benign or malignant brain and spinal cord tumor that arises from glial cells (astrocytes, oligodendrocytes, ependymal cells). "One study recently showed that a risk signature including ATP6AP1 could reasonably predict the prognosis and immune microenvironment of glioma patients." (PMID 36552760, 2022). "More experimental studies of LARP4B and ATP6AP1 in glioma are urgently needed to clarify their specific functions and potential mechanisms." (PMID 36552760, 2022). "In addition, we explored the proteins expressed by REEP6, LARP4B, CWC27, GOLGA2, ATP6AP1 and ERO1B in glioma patients through the HPA database, and REEP6, LARP4B, GOLGA2 and ATP6AP1 showed higher staining intensity in glioma than in normal brain tissue." (PMID 36552760, 2022).
hypogammaglobulinemia (1 paper, 2024). "ALG12-, ATP6AP1-, and MOGS-CDG fall within as the category of predominantly antibody deficiencies since all of them present hypogammaglobulinemia, with low IgG levels." (PMID 38550576, 2024). "Consequently, this likely contributes to the genesis of the antibody deficiency, inflammatory episodes and absent responses to vaccines observed in ALG12-, MOGS-, and ATP6AP1-CDG." (PMID 38550576, 2024).
influenza (1 paper, 2018). An acute viral infection of the respiratory tract, occurring in isolated cases, in epidemics, or in pandemics; it is caused by serologically different strains of viruses (influenzaviruses) designated A, B, and C, has a 3-day incubation period, and usually lasts for 3 to 10 days. "While RNAi of a single gene (e.g. ATP6AP1, COPA, or ARCN1) inhibited replication of many strains of influenza tested here, there were several endemic strains that were not inhibited, and inhibition of diverse strains (e.g. H7N3, H9N2) was particularly weak in the absence of combinatorial RNAi." (PMID 29775471, 2018).
lymph node metastasis (1 paper, 2021). "As for lymph node metastasis, ATP6AP1 levels were significantly greater in N1 than in N0 BC patients (P < 0.05)." (PMID 34228637, 2021).
melanoma (1 paper, 2018). A malignant, usually aggressive tumor composed of atypical, neoplastic melanocytes. "Additionally, we also found up-regulation of two metabolic biosynthesis key players, G6PD and ATP6AP1, in TFAM down samples, suggesting that TFAM levels influence the expression of genes coding for key components of metabolic pathways in melanoma." (PMID 30242167, 2018).
pancreatic cancer (1 paper, 2025). "In pancreatic cancer, ATP6AP1 depletion suppresses lysosomal acidification and IL-1β secretion, suggesting its potential role in modulating pyroptosis-related pathways and TME dynamics." (PMID 40281381, 2025).
Parkinson disease (1 paper, 2011). A progressive degenerative disorder of the central nervous system characterized by loss of dopamine producing neurons in the substantia nigra and the presence of Lewy bodies in the substantia nigra and locus coeruleus. "Second, and more interesting, the oxidative phosphorylation chain, including seven genes (ATP5C1, ATP6AP1, ATP6V1H, COX5B, COX6B1, NDUFA1, and UQCRC1), five of them shared with Huntington's and Parkinson's disease KEGG categories." (PMID 21541025, 2011).
prostate carcinoma (1 paper, 2016). A carcinoma that arises from epithelial cells of the prostate gland. "The Vo-associated glycoprotein Ac45 (ATP6AP1 and ATP6S1) plays a major role in navigating the V-ATPase around prostate carcinoma cells, as it does in the secretory pathway of neuroendocrine cells." (PMID 26912656, 2016).